SBNO2 (strawberry notch homolog 2)
Description:
Acts as a transcriptional coregulator, that can have both coactivator and corepressor functions. Inhibits the DCSTAMP-repressive activity of TAL1, hence enhancing the access of the transcription factor MITF to the DC-STAMP promoter in osteoclast. Plays a role in bone homeostasis; required as a positive regulator in TNFSF11//RANKL-mediated osteoclast fusion via a DCSTAMP-dependent pathway. May also be required in the regulation of osteoblast differentiation (By similarity). Involved in the transcriptional corepression of NF-kappaB in macrophages. Plays a role as a regulator in the pro-inflammatory cascade.
Synonyms: KIAA0963; FLJ00173; Stno; Sno
Tractability: PROTAC: ubiquitination databases record sites on it.
Gene: Protein-coding gene on chromosome 19 (1,107,636 to 1,174,295, reverse strand). Ensembl gene ENSG00000064932.
Gene Ontology:
Biological process: cellular response to interleukin-6; macrophage activation involved in immune response; negative regulation of DNA-templated transcription; regulation of inflammatory response; cellular response to interleukin-11; cellular response to leukemia inhibitory factor; cellular response to lipopolysaccharide; osteoclast differentiation; positive regulation of transcription by RNA polymerase II; regulation of DNA-templated transcription
Genetic constraint (gnomAD): Loss-of-function variants: 90 observed, 105.44 expected, observed/expected ratio (o/e) 0.85, 90% interval 0.72 to 1.02. The synonymous counts are far from expectation, so gnomAD's model fits this gene poorly and the ratio says little. Missense variants: 2,072 observed, 1,629.6 expected, observed/expected ratio (o/e) 1.27, 90% interval 1.23 to 1.32. Synonymous variants: 1,140 observed, 750.16 expected, observed/expected ratio (o/e) 1.52, 90% interval 1.45 to 1.6.
Homologues: Orthologues: macaque SBNO2 (98% identical), chimpanzee SBNO2 (95% identical), dog SBNO2 (86% identical), rat Sbno2 (82% identical), mouse Sbno2 (82% identical), pig SBNO2 (80% identical), guinea pig SBNO2 (80% identical), tropical clawed frog sbno2 (63% identical), zebrafish sbno2b (60% identical), zebrafish sbno2a (58% identical), Drosophila melanogaster sno (43% identical), Drosophila melanogaster CG3491 (41% identical), and 1 more. Paralogues in human: SBNO1 (48% identical).
Diseases named in the same sentence as SBNO2 in open-access papers:
SBNO2 is named in the same sentence as 29 diseases in open-access papers, as found by Europe PMC text mining. Sharing a sentence is not in itself a finding about the gene and the disease. The quoted sentences say what the papers report.
Obesity (3 papers, 2018 to 2021). Accumulation of substantial excess body fat. "The leucocyte epigenome-wide association study of 60 lean and 60 obese young women was performed using the Illumina Infinium HumanMethylation450 BeadChip, and SBNO2 was found to be closely associated with obesity." (PMID 33282955, 2020).
Sepsis (3 papers, 2012 to 2026). Sepsis is defined as life-threatening organ dysfunction caused by a dysregulated host response to infection. "Therapeutic administration of recombinant Sbno2 (rSbno2) in a sepsis-induced ALI mouse model alleviated lung injury, promoted AEC proliferation, and restored barrier function, highlighting Sbno2 as a potential therapeutic target for ALI." (PMID 41491997, 2026). "Our study investigates the role of Sbno2-expressing tissue-resident alveolar macrophages (TR-AMs) in promoting alveolar epithelial cell (AEC) regeneration and barrier function in sepsis-induced ALI." (PMID 41491997, 2026). "Transcriptional regulators like PLAGL2, EBF1, TCF7, KLF10 and SBNO2, previously not described in sepsis, are differentially expressed at early and late time points." (PMID 23009705, 2012).
asthma (2 papers, 2024). "For example, Strawberry Notch Homolog 2 (SBNO2) and Solute Carrier Family 19 Member 1 (SLC19A1) have been linked to asthma in previous GWA studies." (PMID 39108895, 2024).
Crohn disease (2 papers, 2020 to 2024). A gastrointestinal disorder characterized by chronic inflammation involving all layers of the intestinal wall, noncaseating granulomas affecting the intestinal wall and regional lymph nodes, and transmural fibrosis. "Strawberry notch homolog 2 (SBNO2) is a candidate gene in a susceptibility locus with different variants associated with Crohn’s disease and bone mineral density." (PMID 38806456, 2024). "This provides a functional basis for the observed association of SBNO2 variants and methylation signals with inflammatory bowel disease, specifically Crohn’s disease, and bone development." (PMID 38806456, 2024). "Meanwhile, SBNO2 is one of the susceptibility loci of Crohn's disease and ulcerative colitis." (PMID 33282955, 2020). "SBNO2 is one of the susceptibility loci of Crohn's disease, ulcerative colitis, and Peutz–Jeghers syndrome, which may be closely related to many types of tumorigenesis." (PMID 33282955, 2020). "The SBNO2 locus is also differentially methylated in Crohn’s disease but the functional mechanisms are unknown." (PMID 38806456, 2024).
allergic asthma (1 paper, 2024). A asthma with a basis in a pathological type I hypersensitivity reaction. "The genes associated with mucin production (GAL3ST2), leukotriene synthesis (GPX4), Th2-mediated allergic asthma (PTBP1, ZFPM1, SBNO2, and EGFL7), and IgE mediated allergy (PAK2) were also represented in our polygenic prediction models of ICS response." (PMID 38540988, 2024).
ankylosing spondylitis (1 paper, 2024). An autoimmune chronic inflammatory disorder characterized by inflammation in the vertebral joints of the spine and sacroiliac joints. "Indeed, increased expression of SBNO2 has been found in male ankylosing spondylitis associated osteoporosis." (PMID 38806456, 2024).
bipolar disorder (1 paper, 2011). A disorder of the brain that causes unusual shifts in mood, energy, activity levels and the ability to carry out day-to-day tasks. "These genes included SBNO2, CEACAM5, AKAP1, UBC, ACTB, UBB, and FOS for schizophrenia; SEC24C, PGLYRP1, ARHGAP4, RPL22, SLC6A11, and SYK for bipolar disorder; and SRRT, PARK2, LILRA4, STK17A, IGFBP2, and NF1 for major depression." (PMID 22373040, 2011). "Several previously unidentified disease marker genes and drug targets, such as SBNO2 (schizophrenia), SEC24C (bipolar disorder), and SRRT (major depression), were identified based on statistical and topological analyses of the PPI network." (PMID 22373040, 2011). "Apart from this study, SBNO2, SEC24C and SRRT have never been associated with schizophrenia, bipolar disorder, or major depression; these genes did not form PPI with any of our abnormally expressed marker genes, either." (PMID 22373040, 2011).
bladder urothelial carcinoma (1 paper, 2020). "We first evaluated SBNO2 levels in tumour and normal tissues using TIMER and found that SBNO2 expression was significantly elevated in GC (P < 0.001), as well as bladder urothelial carcinoma, cholangiocarcinoma, oesophageal carcinoma, and head and neck squamous cell carcinoma." (PMID 33282955, 2020).
cervical cancer (1 paper, 2022). A primary or metastatic malignant neoplasm involving the cervix. "Several of our high scoring differentially methylated genes (SBNO2 and CUEDC1) are associated with body mass index (BMI)/inflammation and cervical cancer." (PMID 35169479, 2022).
gastric cancer (1 paper, 2020). A primary or metastatic malignant neoplasm involving the stomach. "Our research identified DEGs and key modules contributing to GC and clarified the expression levels and prognostic value of SBNO2, thereby offering novel insights into the development and treatment of gastric cancer." (PMID 33282955, 2020).
glioma (1 paper, 2021). A benign or malignant brain and spinal cord tumor that arises from glial cells (astrocytes, oligodendrocytes, ependymal cells). "The top-ranking genes were related to the TRIP10, NR2F6, ACTN4, SBNO2, and TGFB1L1 genes (p < 0.05), and a link between ACTN4 and TGFB1L1 expression and tumorigenesis was shown in glioma samples." (PMID 34722629, 2021).
Immunodeficiency (1 paper, 2024). Failure of the immune system to protect the body adequately from infection, due to the absence or insufficiency of some component process or substance. "In alignment with this hypothesis, biallelic loss of function variants that affect the catalytic core and both isoforms of SBNO2 cause immunodeficiency and bone malformations." (PMID 38806456, 2024).
schizophrenia (1 paper, 2011). A major psychotic disorder characterized by abnormalities in the perception or expression of reality. "SBNO2 was a gene of which the probe had the lowest P value in the t-test comparing schizophrenia and control samples." (PMID 22373040, 2011).
signet ring cell carcinoma (1 paper, 2020). A usually aggressive, poorly differentiated invasive adenocarcinoma characterized by the presence of malignant glandular cells in which the nucleus is pressed to one side by the presence of intracytoplasmic mucus. "SBNO2 expression was higher in signet ring cell carcinoma than other GC pathological types (P < 0.001)." (PMID 33282955, 2020).
type 2 diabetes (1 paper, 2020). "Some studies reported that SBNO2 increases the risk of cardiovascular disease and type 2 diabetes by increasing BMI, but the mechanism by which SBNO2 leads to GC has not yet been revealed." (PMID 33282955, 2020). "In addition, SBNO2 is also linked to increased risks of cardiovascular disease and type 2 diabetes in conjunction with increasing body weight." (PMID 33282955, 2020).
cancer (4 papers, 2020 to 2026). A tumor composed of atypical neoplastic, often pleomorphic cells that invade other tissues. "In mammals, the Sbno2 gene is associated with cancer cell proliferation and survival, while the Simc1 gene encoded protein, SIMC1, interacts with the CTBP1 protein, which is involved in the ability of cancer cells to evade cell-cycle checkpoints." (PMID 41481677, 2026). "Gaviscon formulations also revealed the downregulation of various genes such as COL6A2, DOHH, MEX3D, SBNO2, which have roles in cancer or chronic disease progression." (PMID 39409043, 2024). "For example, the CpG site cg18608055 (proximal to SBNO2) was associated with POLR2E, an RNA polymerase associated with cancer which also contributed to the significant KEGG cytosolic DNA-sensing pathway." (PMID 38571307, 2024). "The differences in SBNO2 expression according to gender, age, individual cancer stage, tumour grade, histological subtypes, and Helicobacter pylori infection status were explored in patients with GC." (PMID 33282955, 2020). "The expression and prognostic value of SBNO2 were verified in UALCAN, GEPIA2, Human Cancer Metastasis Database, Kaplan–Meier plotter, and TIMER." (PMID 33282955, 2020).
tumor (4 papers, 2010 to 2023). "SBNO2 was identified as the hub gene, which was upregulated in tumour tissues." (PMID 33282955, 2020). "IHC staining of ccRCC TMA revealed that GCLM and MsrA were significantly decreased in tumor tissues, whereas SBNO2 showed no significantly different." (PMID 37496661, 2023).
neurological disease (1 paper, 2022). "To further understand the role of SBNO2 in the CNS and, in particular, in IL-6-mediated neurological disease, we generated a new mouse model with disruption of Sbno2 and crossed these mice with the GFAP-IL6 transgenic mice." (PMID 35624480, 2022). "Here, we demonstrate that SBNO2 is required to constrain IL-6-driven neurological disease." (PMID 35624480, 2022).
SBNO2 also shares sentences with these, for which no sentence is quoted: allergic disease (1 paper); Allergy (1); cardiovascular disease (1); cholangiocarcinoma (1); diabetes (1); gastrointestinal disease (1); head and neck squamous cell carcinoma (1); infection (1); inflammatory bowel disease (1); major depression (1); ulcerative colitis (1).